RAE1 (ribonucleic acid export 1)
Description:
Acts as a mRNA export factor involved in nucleocytoplasmic transport. Plays a role in mitotic bipolar spindle formation. May function in attaching cytoplasmic mRNPs to the cytoskeleton both directly or indirectly.
Synonyms: MRNP41; Mnrp41; Gle2; MIG14; dJ481F12.3; dJ800J21.1
Tractability: Small molecule: it has a high-quality binding pocket. PROTAC: ubiquitination databases record sites on it; its protein half-life has been measured.
Gene: Protein-coding gene on chromosome 20 (57,351,223 to 57,379,211, forward strand). Ensembl gene ENSG00000101146.
Subcellular location: Cytoplasm; Nucleus; Cytoplasm, cytoskeleton, spindle pole; Nucleus envelope
Subcellular location (Human Protein Atlas): Nucleoli fibrillar center; Nucleoplasm
Pathways (Reactome):
Disease: Defective TPR may confer susceptibility towards thyroid papillary carcinoma (TPC); HCMV Early Events; HCMV Late Events; NEP/NS2 Interacts with the Cellular Export Machinery; NS1 Mediated Effects on Host Pathways; Nuclear import of Rev protein; Rev-mediated nuclear export of HIV RNA; SARS-CoV-2 activates/modulates innate and adaptive immune responses; Transport of Ribonucleoproteins into the Host Nucleus; Viral Messenger RNA Synthesis; Vpr-mediated nuclear import of PICs
Metabolism of RNA: Transport of Mature mRNA Derived from an Intronless Transcript; Transport of Mature mRNA derived from an Intron-Containing Transcript; Transport of the SLBP Dependant Mature mRNA; Transport of the SLBP independent Mature mRNA; snRNP Assembly; tRNA processing in the nucleus
Metabolism of proteins: SUMOylation of DNA damage response and repair proteins; SUMOylation of DNA replication proteins; SUMOylation of RNA binding proteins; SUMOylation of SUMOylation proteins; SUMOylation of chromatin organization proteins; SUMOylation of ubiquitinylation proteins
Metabolism: IP3 and IP4 transport between cytosol and nucleus; IP6 and IP7 transport between cytosol and nucleus; IPs transport between nucleus and cytosol; Regulation of Glucokinase by Glucokinase Regulatory Protein
Cell Cycle: Nuclear Pore Complex (NPC) Disassembly
Cellular responses to stimuli: Regulation of HSF1-mediated heat shock response
Immune System: ISG15 antiviral mechanism
Gene Ontology:
Molecular function: protein binding; RNA binding; microtubule binding; ubiquitin binding
Biological process: regulation of mitotic spindle organization; mRNA export from nucleus; nucleocytoplasmic transport; RNA export from nucleus; transcription-dependent tethering of RNA polymerase II gene DNA at nuclear periphery
Cellular component: fibrillar center; mitotic spindle pole; nuclear envelope; nuclear pore; nucleoplasm; cytoplasm; nucleus; spindle pole
Genetic constraint (gnomAD): Loss-of-function variants: 11 observed, 44.25 expected, observed/expected ratio (o/e) 0.25, 90% interval 0.16 to 0.41. The upper end of that interval is the gene's LOEUF score, 0.41, which puts it in group 1 of 6, group 1 being the genes least tolerant of losing a copy. Missense variants: 253 observed, 456.08 expected, observed/expected ratio (o/e) 0.55, 90% interval 0.5 to 0.62. Synonymous variants: 160 observed, 155.52 expected, observed/expected ratio (o/e) 1.03, 90% interval 0.9 to 1.17.
Homologues: Orthologues: chimpanzee RAE1 (100% identical), pig RAE1 (99% identical), guinea pig RAE1 (99% identical), mouse Rae1 (99% identical), rat Rae1 (98% identical), macaque RAE1 (94% identical), tropical clawed frog rae1 (93% identical), zebrafish rae1 (91% identical), rabbit RAE1 (79% identical), Drosophila melanogaster Rae1 (65% identical), Caenorhabditis elegans rae-1 (52% identical), Drosophila melanogaster CG12782 (35% identical). Paralogues in human: BUB3 (32% identical), DNAAF10 (20% identical).
Diseases named in the same sentence as RAE1 in open-access papers:
RAE1 is named in the same sentence as 55 diseases in open-access papers, as found by Europe PMC text mining. Sharing a sentence is not in itself a finding about the gene and the disease. The quoted sentences say what the papers report.
viral infection (13 papers, 2010 to 2024). "During viral infection, the matrix protein of vesicular stomatitis virus inhibits nuclear export of host cell mRNAs by binding to the mRNA export factor RAE1." (PMID 39080077, 2024). "Together, these data indicate that the Sarbecovirus accessory protein ORF6 prevents bidirectional nucleocytoplasmic transport through its interactions with Rae1 and Nup98, leaving host cells incapable of responding to viral infection." (PMID 33849972, 2021). "Several virus-encoded proteins were reported to directly interact with the Rae1-Nup98 complex to inhibit the export of mRNA during viral infections." (PMID 35096974, 2021). "Mouse fibroblasts normally express low levels of Raet1 mRNA and protein, but RAE-1 expression is upregulated in response to cell stress, including viral infection." (PMID 27874833, 2016). "Nonetheless, the role of p110α PI3K in regulating RAE-1 expression during both viral infection and transformation is an intriguing finding that deserves further investigation." (PMID 21966273, 2011). "In this manuscript, we focused on the involvement of cellular pathways that are activated during viral infection in the expression of RAE-1." (PMID 21966273, 2011). "RAE-1 is overexpressed in tumor cell lines and its expression is induced after viral infection and genotoxic stress." (PMID 20976056, 2010). "Thus, using a 3-fold difference as a selection criterion focused attention on gene expression changes in response to virus infection that were greater than the effects of silencing Rae1 expression in mock-infected cells." (PMID 23028327, 2012). "Because our data suggested that early events upon viral infection are necessary to induce RAE-1, we hypothesized that manipulation of some of these cellular pathways are involved in the induction." (PMID 21966273, 2011). "Future study of how CebN co-opts NUPs and Rae1 will not only enhance our understanding of how C.t. establishes a persistent infection despite a robust host response but may also identify druggable targets applicable to both bacterial and viral infections." (PMID 38712050, 2024). "Differentially expressed genes in the viral infection category (174 genes) indicated that keratinocytes had down-regulated genes involved in host gene transcription (DDX56, SMARCA2) and RNA transportation and processing (NUP98, RAE1, XAB2, RBM17, EXOSC10)." (PMID 34552595, 2021). "Knockdown of Rae1, mTor, Nup88 or Nup214 did not restore VP2 expression under mutant CrPV(R146A) virus infection compared to wild-type infection, similar to that observed in the control dsRNA treated cells." (PMID 36455064, 2022).
breast carcinoma (11 papers, 2013 to 2023). "In this study, we evaluated the metastatic properties of RAE1-overexpressing breast cancer cells both in 3D culture systems and in vivo xenograft models, and further demonstrated the molecular mechanisms underlying RAE1-mediated tumor progression." (PMID 30814639, 2019). "In particular, ZNF217, which is located on 20q13 near the locus that encodes RAE1, was previously reported as a novel breast cancer gene along with EGFR1, ERBB2, and PPMID26." (PMID 28181567, 2017). "Instead, RAE1 gene amplification and consequent RAE1 overexpression appear to be important risk factors in breast cancers." (PMID 28181567, 2017). "The nucleoporin Rae1 (Gle2) plays an important role in RNA export and is linked to breast cancer pathology." (PMID 24429466, 2014). "Some of them are Ribonucleic acid exports 1 (Rae1) linked to breast cancer pathophysiology and Nup88 which is overexpressed in ovarian cancer as well as in a broad spectrum of sarcomas, lymphomas and mesotheliomas." (PMID 23343205, 2013). "RAE1 is involved in the nuclear output of poly (A)+ RNA and is negatively correlated with breast cancer prognosis, which is similar to the results found for HCC in the current study." (PMID 34262594, 2021). "In this study, we investigated how RAE1 contributes to invasion and metastasis of breast cancer, three-dimensional (3D) culture system and xenograft models." (PMID 30814639, 2019). "To further explore the functional role of RAE1 in breast cancer progression in vivo, we evaluated the effects of RAE1 on the metastasis in a breast cancer xenograft model." (PMID 30814639, 2019). "Taken together, these data demonstrate that RAE1 contributes to breast cancer metastasis by regulating a key EMT-inducing factor ZEB1 expression, suggesting its potential as a therapeutic target." (PMID 30814639, 2019). "Together, these data suggest that ZEB1 functions as a key component of RAE1-mediated EMT in breast cancer." (PMID 30814639, 2019). "Among various breast cancer cell lines, we found that RAE1 is expressed highly in BT474, but it is expressed relatively low in MDA-MB-453, T47D, and MDA-MB-231." (PMID 30814639, 2019). "We previously showed that Ribonucleic acid export 1 (RAE1) is dysregulated in breast cancer and its overexpression leads to aggressive breast cancer phenotypes by inducing EMT." (PMID 30814639, 2019). "With the expectation that RAE1 would also be a useful target for cancer therapy, we carried out functional studies in breast cancer cell lines and found that RAE1 contributes to aggressive cancer cell phenotype and induces EMT18." (PMID 30814639, 2019). "Here, we evaluated the functional capacity of RAE1 in breast cancer metastasis by using a three-dimensional (3D) culture system and xenograft models." (PMID 30814639, 2019). "To investigate the precise effects of RAE1 overexpression in breast cancer, we carried out 3D cell culture analysis with stable MCF7 cell lines overexpressing RAE1 (MCF7:RAE1 #1, 2, and 3) and empty vector (MCF7:emp vec #1, and 2)." (PMID 30814639, 2019). "Considering that EMT enhances the metastatic potential of breast cancer, our results support the relationship between RAE1 activity and breast cancer aggressiveness." (PMID 30814639, 2019). "As expected, RAE1 downregulation reduced the invasive and migratory capacities of breast cancer cells, implicating a possible role of RAE1 in breast tumour cell invasion and metastasis." (PMID 28181567, 2017). "As RAE1 induces EMT and invasion, we examined the potential correlations of clinicopathological features with RAE1 expression in patients with breast cancer." (PMID 28181567, 2017). "In humans, a positive correlation has been found between RAE1 copy number abnormalities and gene amplification in breast cancer cells." (PMID 28181567, 2017). "In our samples, although 25.5% (25/98) of breast cancer tissues were defined as RAE1-positive, we were unable to find any correlations with various clinicopathological features." (PMID 28181567, 2017).
breast carcinoma (continued). "Among 825 evaluated patients with breast cancer, 16% (n = 129) harboured abnormalities in RAE1, including amplification, mRNA up/downregulation, and missense mutations." (PMID 28181567, 2017). "An in silico analysis of data retrieved from GENT and cBio-Portal identified RAE1 upregulation in breast cancer tissues relative to normal breast cells." (PMID 28181567, 2017). "This is the first study to investigate in depth the functional roles and clinical significance of RAE1 in breast cancer using both in vitro system and patient samples, together with an in silico analysis." (PMID 28181567, 2017). "Through RAE1 overexpression and knockdown studies, we revealed that RAE1 enhanced aggressive breast cancer cell phenotypes by inducing epithelial-mesenchymal transition (EMT) signals." (PMID 28181567, 2017). "A comparison of 271 normal breast tissues with 2,658 breast cancer tissues clearly demonstrated significant upregulation of RAE1 in the latter." (PMID 28181567, 2017). "RAE1 overexpression was detected in breast cancer cells, which could promote proliferation of human cancer cells by the Hippo signaling pathway." (PMID 35751040, 2022). "Furthermore, RAE1 overexpression was positively correlated with the histologic grade and a poor prognosis in patients with breast cancer and colorectal cancer." (PMID 35751040, 2022). "RAE1 downregulation reduced the migration and invasion capabilities of breast cancer cells." (PMID 35751040, 2022). "Elevated RAE1 expression indicated a poor outcome in breast cancer patients." (PMID 30814639, 2019). "In addition, our confirmation of RAE1-positive patients among a larger population of patients with breast cancer and the relationship of this parameter with clinicopathological data via TMA analysis provides worthwhile information." (PMID 28181567, 2017). "In this study, which aimed to explore the relationship between RAE1 expression and breast cancer progression, we performed functional studies of breast cancer cell lines and analysed the relationships of RAE1 expression with clinicopathological features and prognosis in patients with breast cancer." (PMID 28181567, 2017). "After observing that RAE1 induced migratory and invasive abilities in breast cancer cells in our in vitro system, we tested whether the EMT mediated this phenomenon." (PMID 28181567, 2017). "Given the findings regarding the relationship between RAE1 overexpression and clinicopathological significance in breast cancer, RAE1 might represent a new therapeutic target and prognostic marker." (PMID 28181567, 2017). "Our important findings, namely the correlations of RAE1 overexpression with a high histologic grade and poor prognosis and identification of a functional role of RAE1 in cancer cell migration and invasion, strongly support the notion that RAE1 contributes to breast cancer progression." (PMID 28181567, 2017). "However, the precise functional role of RAE1 in breast cancer remains to be determined." (PMID 28181567, 2017). "In conclusion, our study demonstrated that RAE1 promotes progression of breast cancer cells by activating ZEB1 at the transcription level and revealed the positive correlation between RAE1 and ZEB1 in breast cancer metastasis." (PMID 30814639, 2019). "However, the low incidence of RAE1 mRNA downregulation or missense mutation events in human breast cancers suggests that RAE1 deficiency might not be a major driving force in this type of cancer." (PMID 28181567, 2017). "We used breast cancer tissues from 98 patients to construct a TMA, which was subjected to immunohistochemistry (IHC) to evaluate RAE1 protein expression." (PMID 28181567, 2017). "However, the exact roles of RAE1 and related abnormalities in breast cancer remain unclear." (PMID 28181567, 2017). "Taken together, our in vitro data suggest that RAE1 induces EMT and thus promotes the migration and invasion of breast cancer cells." (PMID 28181567, 2017).
breast carcinoma (continued). "CDK12, LASP1, RAE1, C17orf57, NSF, and USH2A were partners of out-of-frame, but not in-frame, fusion genes here and in other massively parallel sequencing analyses of breast cancers 12,15–17,41–43." (PMID 24395524, 2014). "RAE1 overexpression could facilitate EMT to lead to an invasive ductal histology and a high histological grade in breast cancer." (PMID 35751040, 2022). "Finally, only 1 (BCAS4/BCAS3), 1 (BSG/NFIX), 2 (STX16/RAE1, RAB22A/MYO9B) and 0 fusions have been reported by all the tools within the considered breast cancer cell lines." (PMID 28114882, 2017). "The CpG ODN administration up-regulated RAE-1, H60 and MULT-1 on breast cancer cells, H60 and MULT-1 on melanoma cells, and made them only capable of forming dramatically smaller tumors in syngeneic mice, implying that the CpG ODN induced retardation of the tumors by up-regulating NKG2DL." (PMID 27448968, 2016). "Of the out-of-frame validated chimeras, we identified recurrent expressed chimeric transcripts involving CDK12 (2.7%) and RAE1 (1%), and DNA rearrangements involving C17ORF57 (0.5%), NSF (0.5%), USH2A (0.5%), and LASP1 (1%) from unselected breast cancers in external datasets 12,15–17,41–43." (PMID 24395524, 2014). "So, CUG2, E2F8, RAE1, and PTPA might not be the downstream targets of MBNL1-AS1 in breast cancer cells." (PMID 35518784, 2022).
lymphoma (5 papers, 2013 to 2022). A malignant (clonal) proliferation of B- lymphocytes or T- lymphocytes which involves the lymph nodes, bone marrow and/or extranodal sites. "Leukemia and lymphoma target cell lines for cytotoxicity assays were selected based on the expression of the NK cell activating ligands RAE‐1 and MULT‐1 (detected via NKG2D) and CD155 (detected via DNAM1)." (PMID 32052406, 2020). "RAE-1 expression was highly dependent on STING activation; RAE-1, an IRF3 responsive gene has previously been shown to be regulated by the STING-dependent DNA sensor pathway in lymphomas." (PMID 36483558, 2022).
leukemia (4 papers, 2016 to 2023). A malignant (clonal) hematologic disorder, involving hematopoietic stem cells and characterized by the presence of primitive or atypical myeloid or lymphoid cells in the bone marrow and the blood. "With respect to EMB (XPO1 in mammals) and RAE1, their mammalian homologs have been shown to contribute to NA9-induced leukemia through their association with the FG / GLFG motifs and GLEBS domain of NA9, respectively, which appears to interfere with nucleocytoplasmic transport." (PMID 34383740, 2021). "Besides, the expanded CD8+ T cells expressed up-regulated NKG2D and could reinforce the clearance of RAE-1 expressing leukemia cells in mice." (PMID 27448968, 2016).
melanoma (4 papers, 2016 to 2025). A malignant, usually aggressive tumor composed of atypical, neoplastic melanocytes. "Consistent with the observation, RAE-1 gene-transfection was found resulted in rapid rejection of EL4 (a thymoma), RMA (a T-cell lymphoma) and B16 (a melanoma) cells in syngeneic mice; and 10-fold up-regulated RAE-1 led to less lung metastatic loci from by i.v. transfused B16 cells." (PMID 27448968, 2016). "Co-culturing the NK cells with either EO771 breast adenocarcinoma cells that express MHC-I molecules and Rae-1 or B16F10 melanoma cells that express none of those molecules in vitro resulted in dose-dependent tumor cell death and up-regulation of IFN-γ production by the NK cells." (PMID 39835538, 2025).
glioma (3 papers, 2016 to 2023). A benign or malignant brain and spinal cord tumor that arises from glial cells (astrocytes, oligodendrocytes, ependymal cells). "TCGA data indicates Rae1 amplification in a range of cancers and Rae1 protein levels accumulate in gliomas, a tumor type where loss of Mer and Hippo Pathway function are frequently implicated." (PMID 27494403, 2016). "The CT2A-TRP2-β2mKO line was found to highly express the non-classical MHC-I molecules RAE-1 and MULT-1, findings that were recapitulated with the additional glioma line GL261-OVA-β2mKO." (PMID 37537301, 2023).
hepatocellular carcinoma (3 papers, 2017 to 2022). A malignant tumor that arises from hepatocytes. "Bio-CS nanomaterials stimulated an immune response in hepatoma cells via increased expression of GM-CSF, IL-21 and Rae-1 markers." (PMID 28938619, 2017).
liver fibrosis (3 papers, 2012 to 2023). "Our findings revealed a new role for Cyp4a in retinol metabolism in the development of hepatic fibrosis, and they highlight Cyp4a12/Rae-1 signals as possible therapeutic targets for antifibrotic medicines." (PMID 37161575, 2023). "The authors showed that hepatic NK cells killed activated HSCs via retinoic acid early inducible 1 (RAE1)/NKG2D dependent and tumor necrosis factor-related apoptosis-inducing ligand (TRAIL)-dependent mechanisms, thereby inhibited liver fibrosis." (PMID 22235358, 2012).
ovarian carcinoma (3 papers, 2013 to 2022). A malignant neoplasm originating from the surface ovarian epithelium. "Of note, the cis direct target gene for SE60, RAE1, has previously been associated with invasion in ovarian cancer and has been shown to promote EMT in breast cancer." (PMID 35869079, 2022).